GZMA (granzyme A)
Diseases named in the same sentence as GZMA in open-access papers (continued):
Sharing a sentence is not in itself a finding about the gene and the disease.
colon cancer (11 papers, 2018 to 2024). "Our findings revealed a pronounced expression of GSDMB in colon cancer cells, with GZMA and IFN-γ frequently co-expressed within CD8+TILs." (PMID 39030523, 2024). "To confirm the prognostic significance of CD8+TILs in colon cancer, we assessed the clinical outcome values associated with CD8+TILs, GZMA+ cells and IFN-γ+ cells." (PMID 39030523, 2024). "In human eosinophils, the induction of apoptosis in colon cancer cells was shown to be mediated by granzyme-A and TNF-α." (PMID 31717819, 2019). "Moreover, it is imperative for future studies to unravel the precise mechanisms by which GZMA+IFN-γ+CD8+TILs target GSDMB-expressing colon cancer cells and facilitating pyroptosis." (PMID 39030523, 2024). "However, we provide a further link between mutations in GZMA and perforins and high CYT in colon cancer." (PMID 34316699, 2021). "In this study, the average expressions of CD8A, CD8B, GZMA, GZMB, and PRF1 genes were used to represent level of CTL in colon cancers." (PMID 38327746, 2024). "Our research sheds light on the clinical implications and functional roles of CD8+T cells expressing GZMA and IFN-γ, as well as colon cancer cells expressing GSDMB." (PMID 39030523, 2024). "In summary, it is crucial to further explore how CD8+TILs co-expressing GZMA and IFN-γ regulate GSDMB in colon cancer epithelial cells and their impact on patient prognosis." (PMID 39030523, 2024). "In this study, we utilized mIHC to examine the spatial distribution and clinical significance of GZMA, IFN-γ, and GSDMB within TME of human colon cancer patients." (PMID 39030523, 2024). "In contrast, the expression of GZMA and IFN-γ in normal colon tissues were significantly upregulated compared to those in colon cancer tissues (P < 0.001)." (PMID 39030523, 2024). "We identified that in APC-wt/MSS colon cancer, the expressions of PD-1, PD-L1, CTLA4, and CYT (GZMA and PRF1) were increased." (PMID 35937946, 2022). "Moreover, investigating the effects of GZMA+IFN-γ+CD8+TILs and GSDMB+ tumor epithelial cells on signaling pathways within the colon cancer TME is essential." (PMID 39030523, 2024). "However, the interaction between GZMA-expressing CD8+T cells and GSDMB-expressing tumor cells in colon cancer remains poorly understood." (PMID 39030523, 2024). "Our data showed that compared to the control group, SuperPDL1exo could enhance infiltration of CD8+ T cells in tumors; increase the expression of cytotoxic granules such as perforin, granzyme B, and granzyme A; and exert antitumor effects in the MC38 colon cancer model." (PMID 37529049, 2023). "In 2020, Zhou and colleagues reported that granzyme A (GzmA) derived from natural killer (NK) and/or CD8+ T cells cleaved GSDMB at K244 (major cleavage site) and K229 (minor cleavage site), which was conserved in GSDMBiso1-4 in a colon cancer cell line, resulting in pyroptosis in cancer cells." (PMID 37781519, 2023).
ovarian carcinoma (8 papers, 2018 to 2025). A malignant neoplasm originating from the surface ovarian epithelium. "This is a promising result as in clinical settings elevated granzyme A and B may be associated with improved outcomes in advanced, treated ovarian cancer and have been linked with survival in ovarian cancer." (PMID 39170449, 2024). "A similar non-significant association of (individual or simultaneous) high GZMA and PRF1 expression with better effect on patient survival could also be observed in TCGA-MESO, ovarian cancer (GSE13876 and GSE49997), TCGA-STAD, TCGA-THCA, and TCGA-UCEC." (PMID 29515971, 2018). "However, some PYAGs with CNV gain, such as GSDMD, TP63, PRKACA, PJVK and CASP4, showed downregulated mRNA expression in ovarian cancers, and some PYAGs with CNV loss, such as IL18, GPX4, GZMA, NLRP6 and CASP6, showed upregulated mRNA expression in ovarian cancers." (PMID 36707884, 2023). "What is more, the concentrations of GZMA in patients with ovarian cancer were substantially increased in comparison to that in patients with ovarian cystadenomas or ovarian teratomas, which is similar to our results that the high expression of GZMA was connected with poor OS of COAD patients." (PMID 35912258, 2022). "NKT cells strongly expressed the GZMB, GZMA, GZMH, and PRF1 genes, indicating that they promoted tumor cytotoxicity in ovarian cancer." (PMID 35935940, 2022). "Genes related with ICB, including CTLA-4, PD-L2, PD-L1, CD8A, GZMA, and PRF1, were all lowly expressed in type III ovarian cancer." (PMID 32793247, 2018). "The expression of PD-L2, GZMA, and PRF1 in type I and II ovarian cancer was higher than that in type III ovarian cancer." (PMID 32793247, 2018). "The higher expression of PD-L1, CD8A, GZMA, and PRF1 in type I and II ovarian cancer indicated that these patients would tend to gain more benefit from anti-PD-1/PD-L1 therapy." (PMID 32793247, 2018). "Genes related to ICB (CTLA-4, PD-L1, and PD-L2) and cytotoxic lymphocytes (CD8A, GZMA, and PRF1) were all highly expressed in type I and II ovarian cancer." (PMID 32793247, 2018). "Our results demonstrate that Lv-PD1-γδ T cells can generate functional anti-PD-1 antibodies to block the PD-1/PD-L1 inhibitory pathway, resulting in enhanced cytotoxicity and improved therapeutic efficacy in ovarian cancer by secreting high levels of IFN-γ, TNF-α, and granzyme A/B." (PMID 37857598, 2023).
influenza (6 papers, 2008 to 2025). An acute viral infection of the respiratory tract, occurring in isolated cases, in epidemics, or in pandemics; it is caused by serologically different strains of viruses (influenzaviruses) designated A, B, and C, has a 3-day incubation period, and usually lasts for 3 to 10 days. "The moderate induction of granzyme A mRNA in influenza infected mice was unaltered by smoke." (PMID 18627612, 2008). "In vaccinated volunteers, the expression of Granzyme A, Perforin and CD57 on influenza HLA A*02 M158–66 antigen specific cells was higher than non-vaccinated volunteers before and after challenge despite a similar frequency of antigen specific cells." (PMID 23658773, 2013). "The top five genes of each of the two clusters (NK cell activity; NK and T‐cell activity) that were most closely correlated with influenza antibody titers had seven genes (SPON2, AKR1C3, PRF1, FCRL6, GZMA, CSTK, NKG7) which belong to the aging signature genes of IL‐7Rαlow EM CD8+ T cells." (PMID 31044512, 2019).
skin melanoma (6 papers, 2018 to 2022). "In TCGA-ACC, skin melanoma, and bladder cancer, CYT was associated with an improved patient outcome and high levels of both GZMA and PRF1 synergistically affected patient survival in these cancers." (PMID 29515971, 2018). "To determine whether CYT-high is a good prognostic indicator, we explored the overall survival of skin melanoma patients having high or low expression levels of GZMA and PRF1, using SynTarget." (PMID 33779796, 2021). "TMBhigh skin melanomas also correlate with intratumoral immune cytolytic activity (CYT), defined by the expression of granzyme A and perforin 1, both secreted by effector cytotoxic CD8+ T-cells and NK cells against their target cells." (PMID 36389735, 2022). "In specific, GZMA protein expression (nuclear or cytoplasmic/membranous) was medium only in one skin melanoma; whereas, low in six and absent in five out of twelve skin tumors." (PMID 33779796, 2021). "In addition, the correlation between IL32 and various genes of cytolytic molecules, such as GZMA, GZMB, and PRF1, is positive, suggesting that IL32 mRNA expression may increase patient survival through the infiltration and activation of anticancer effector cells in cutaneous melanoma." (PMID 34682815, 2021).
tuberculosis (6 papers, 2016 to 2025). A chronic, recurrent infection caused by the bacterium Mycobacterium tuberculosis. "Similar findings have been reported in other septic patients with human bacteraemia, tuberculosis and typhoid fever where high serum levels of GzmA have been detected 41-43 suggesting that this protease may have extracellular effects during other infectious diseases." (PMID 33664861, 2021). "For example, several studies have shown that granzyme A is highly expressed in patients with tuberculosis and may represent a promising diagnostic marker distinct from IFN-γ to discriminate between patients with tuberculosis and other pulmonary diseases." (PMID 30340642, 2018). "Altogether, our findings are in apparent contradiction with previously published in vitro results and suggest that Granzyme A does not have a crucial role in vivo in the protective response to tuberculosis." (PMID 27055232, 2016). "When combined with four additional genes (LTF, guanylate binding protein 5, CD64, and Granzyme A), FCGRIB demonstrated the ability to effectively differentiate between TB disease and latent tuberculosis infection (LTBI) in small case-control investigations." (PMID 39097795, 2024). "They specifically focused on comparing the expression profiles of three genes – guanylate binding protein 5, granzyme A, and CD64 – in blood specimens obtained from patients diagnosed with TB disease, non-tuberculosis pneumonia, or Asthma." (PMID 39097795, 2024).
Arthritis (5 papers, 2017 to 2023). Inflammation of a joint. "So CHIKV infection (day 2) and arthritis (day 6) stimulate immune and inflammation pathways that overlap with those stimulated by GZMA, but GZMA only plays a minor role in stimulating these pathways during CHIKV viremia (day 2) and arthritis (day 6)." (PMID 35119362, 2022). "Hence, the genetic background and the presence of the full-length Nnt gene, rather than the loss of GZMA expression, were shown to be responsible for the ameliorated CHIKV arthritis phenotype of Gzma−/− mice." (PMID 37014125, 2023). "This proposes GzmA inhibition as a therapeutic strategy in fighting CHIKV-induced arthritis." (PMID 34529743, 2021). "As described afore, GzmA inhibition could repress CHIKV-mediated arthritis, and GzmM might also contribute to inflammation-mediated damage." (PMID 34529743, 2021). "Previous studies also showed that Gzma−/− mice had a pronounced reduction in foot swelling and arthritis compared to wild-type C57BL/6J mice, suggesting a pro-inflammatory role of GZMA in CHIKV infection." (PMID 37014125, 2023). "Targeting and inhibiting the activity of GZMA may, therefore, be a potential therapeutic approach for CHIKV-induced arthritis." (PMID 37014125, 2023). "We show herein that this mouse strain is on a mixed 6J/6N genetic background and contains a full-length Nnt gene, with both Nnt and other 6N background genes, rather than loss of GZMA expression, responsible for the ameliorated CHIKV arthritis phenotype." (PMID 35119362, 2022). "As CHIKV-infected GzmaS211A mice (on a 6J background) show no reduction in foot swelling, the data argues that GZMA is not a major player in CHIKV arthritis." (PMID 35119362, 2022). "GzmA secretion by Th1 CD4 T cells is thus unlikely to be a major driver of CHIKV arthritis." (PMID 31993061, 2019). "Granzyme A (rather than IFNγ) from differentiated NK cells and CD4 T cells thus appears to be an important driver of CHIKV arthritis, with granzyme A dispensable for control of CHIKV infection." (PMID 28207896, 2017).
hepatocellular carcinoma (5 papers, 2021 to 2023). A malignant tumor that arises from hepatocytes. "Four genes, CD14, NPC2, IER3, and GZMA, have been extensively investigated in hepatocellular carcinoma." (PMID 37354485, 2023). "For other cell types, potential strong interactions between CAFs and T cells were observed via ligand–receptor interaction, such as GZMA‐F2R, to induce tumour suppression and T cell‐mediated killing of tumour cells between cytoxic T and tumour cells in hepatocellular carcinoma." (PMID 36855810, 2023).
osteosarcoma (5 papers, 2020 to 2023). A usually aggressive malignant bone-forming mesenchymal neoplasm, predominantly affecting adolescents and young adults. "By the Lasso Cox regression analysis, 6 key PRGs were screened for constructing the optimal model, namely CHMP4C, GZMA, BAK1, CASP1, CASP6, and GSDMA, and a six PRGs signature was successfully constructed for osteosarcoma." (PMID 36244998, 2022). "Five of the seven immune-related genes (CDCA7, GZMA, SLC7A7, VAMP8, and EVI2B) were highly expressed in the osteosarcoma group, while two of these immune-related genes (IFITM3 and ACTA2) were lowly expressed." (PMID 33384961, 2020). "Further analysis on the differences between metastatic and non-metastatic samples revealed six intersection genes—AIM2, RPL22L1, PDPN, PKIB, GZMA, and MDM2—that related to metastasis potential of osteosarcoma and the observed gene expression differences resulted from the changes in methylation." (PMID 36072791, 2022). "The heatmap of these seven immune-related genes expression level in GSE42352 indicated that five of these genes (CDCA7, GZMA, SLC7A7, VAMP8, and EVI2B) were highly expressed in the osteosarcoma group, but two of these genes (IFITM3 and ACTA2) were highly expressed in the normal group." (PMID 33384961, 2020).
rheumatoid arthritis (5 papers, 2017 to 2022). A chronic, systemic autoimmune disorder characterized by inflammation in the synovial membranes and articular surfaces. "Glucocorticoid signaling also regulates the immune system, thus it is not surprising that two immunity-related pathways emerged in the analyses: pathway involved in a role of macrophages, fibroblasts and endothelia cells in rheumatoid arthritis pathway, and the granzyme A signaling pathway." (PMID 29249826, 2017). "Based on the Gene Expression Omnibus (GEO) database, GZMA, PRC1 and TTK were enriched in the innate immune cell-mediated immune response and immune-related biological processes, validating them as potential targets for rheumatoid arthritis (RA) therapy." (PMID 35651940, 2022). "Circulating granzyme A levels have previously been shown to be elevated in patients suffering from infections with dengue, EBV, HIV-1, primary CMV, malaria, and bacteria, and also in rheumatoid arthritis patients." (PMID 28207896, 2017).
autoimmune disease (4 papers, 2021 to 2022). A disorder resulting from loss of function or tissue destruction of an organ or multiple organs, arising from humoral or cellular immune responses of the individual to their own tissue constituents. "GZMA mediates apoptosis and cell scorching, induces the release of inflammatory factors, is involved in the body’s defense against pathogenic bacterial infections, and is associated with the development of certain autoimmune diseases." (PMID 36591509, 2022). "Abnormal expression of GZMA has been found in autoimmune diseases such as SLE and Sjögren’s syndrome, which shows that the gene has a very objective intervention value." (PMID 36505419, 2022). "Studies have elucidated that Tfh cells and GZMA play a crucial role in infection and autoimmune diseases." (PMID 34484236, 2021). "GzmA can also participate in inflammatory and autoimmune diseases." (PMID 36362341, 2022). "In addition to its cytotoxic activity against tumor and virus-infected cells together with perforin, GZMA is involved in innate host during inflammatory and autoimmune disorders in the absence of perforin." (PMID 34484236, 2021).
co-infection (4 papers, 2016 to 2023). "Consistent with this, we also found HIV infection elevated the production of perforin in CD4+ T cells, and HIV/TB co-infection had more granzyme A secretion in CD4+ T cells than HIV infection and TB alone." (PMID 37483385, 2023). "Compared with healthy controls, TB and HIV/TB co-infection had higher frequency of TCRαβ+ DNT cells secreting Granzyme A (p = 0.046; p = 0.005)." (PMID 36443691, 2022). "Our findings suggested that in HIV/TB co-infection, the enhanced granzyme A production in both CD4+ CTLs and CD8+ CTLs might be critical for the clearance of viruses and MTB." (PMID 37483385, 2023). "We found both TB and HIV infection elevated the production of granzyme A and perforin in CD8+ T cells, and HIV/TB co-infection further enhanced granzyme A production in CD8+ T cells." (PMID 37483385, 2023). "Compared with HCs and patients with TB, a lower percentage of tumor necrosis factor α (TNF-α) secreting DP T cells and a higher percentage of granzyme A-secreting DP T cells were observed in patients with HIV mono-infection and HT coinfection, respectively." (PMID 35712309, 2022). "In TB and HIV/TB co-infection, TCRαβ+ DNT cells secreted more granzyme A (p = 0.002; p = 0.002) and perforin (p < 0.001; p = 0.017) than CD4+ T cells but similar to CD8+ T cells." (PMID 36443691, 2022). "Consistent with this, the analysis and comparison of granzyme A and perforin secretion of CD4+ T cells, CD8+ T cells and TCRαβ+ DNT cells also showed TCRαβ+ DNT cells might display cytotoxic T cells-like function in TB and HIV/TB co-infection." (PMID 36443691, 2022). "We speculated that the secretory and regulatory pathways of granzyme A might be independent of the secretory pathway of perforin, and those pathways might be differently affected in TB and HIV/TB co-infection." (PMID 37483385, 2023).
gastric cancer (4 papers, 2018 to 2024). A primary or metastatic malignant neoplasm involving the stomach. "In summary, low expression of GZMA is a positive biomarker of response and prognosis in patients with advanced gastric cancer receiving first-line β-glucan combined immunochemical therapy." (PMID 39253086, 2024). "Therefore, high serum GZMA expression at baseline revealed to be an independent factor for first-line immunotherapy combined with chemotherapy for gastric cancer." (PMID 39253086, 2024). "Low expression of GZMA may still be a positive biomarker of response and prognosis in patients for first-line combination therapy with β-glucan in gastric cancer." (PMID 39253086, 2024).
glioma (4 papers, 2021 to 2024). A benign or malignant brain and spinal cord tumor that arises from glial cells (astrocytes, oligodendrocytes, ependymal cells). "Increased expression of granzyme A, granzyme B, and perforin by intratumoral CD4+ CTLs in gliomas suggests these cells to be a positive prognostic marker for glioma survival." (PMID 37304294, 2023). "TIME cluster A exhibited the high expression profiles of ZEB1, TNF, and LAG3; while GZMA, CXCL9, CXCL10, and CD8A were relatively overexpressed in TIME cluster C. EMT is a common process of paramount importance in glioma occurrence and invasion." (PMID 34650972, 2021).
lung adenocarcinoma (4 papers, 2021 to 2025). A carcinoma that arises from the lung and is characterized by the presence of malignant glandular epithelial cells. "Lastly, although the authors observed inverse correlations between EPHA2 and CTL gene signatures in human pancreatic cancer, we did not discover any consistent trends between EPHA2 and CD3E, CD8B, GZMA, GZMB, PRF1, or IFNG expression from the TCGA lung adenocarcinoma dataset." (PMID 40867322, 2025).
lung carcinoma (4 papers, 2023 to 2025). "Flow cytometry analysis also revealed the presence of CD45+CD8−CD4+GZMA+ cells in the MPE of lung cancer patients." (PMID 40959273, 2025). "Similarly, the mRNA expression levels of granzyme A, B and M were downregulated in PBMCs from lung cancer patients, supporting a reduced cytotoxic capacity of peripheral blood cells in the context of cancer." (PMID 40895524, 2025).